FTO (FTO alpha-ketoglutarate dependent dioxygenase)
Diseases named in the same sentence as FTO in open-access papers (continued):
Sharing a sentence is not in itself a finding about the gene and the disease.
Obesity (continued). "Many studies, also in the pediatric population, focus on single nucleotide polymorphisms (SNPs) in genes with a well-described relationship with obesity, such as FTO, or genes, whose role in obesity is recently gradually being discovered, as the PLAG1 gene." (PMID 34063412, 2021). "A long-time LTSB accentuated the effect of FTO rs8050136 on obesity and central obesity (OR = 1.27, 95%CI:1.05–2.36; OR = 1.44, 95%CI:1.06−1.97)." (PMID 33668547, 2021). "Specific variants in FTO have been reported to predispose individuals to type 2 diabetes mellitus (T2DM) and obesity, which are common risk factors for cardiovascular diseases." (PMID 34221238, 2021). "The relative risk analysis for of FTO, MC4R, ACE and MTHFR gene polymorphism with obesity and dyslipidaemia is performed independently in both the studied populations." (PMID 34414818, 2021). "It is pertinent to note that out of the total 10 obesity related SNPs from FTO, ADIPOQ and LEPR genes considered in this study, seven were involved in pair-wise interactions and associated with either risk or protective nature towards manifestation of T2DM." (PMID 34784930, 2021). "In conclusion, our study confirms the association between common genetic variants in the FTO and TUB genes and increased risk for developing obesity in individuals of African and Hispanic descent respectively." (PMID 33983957, 2021). "FTO knockout mice exhibit growth retardation, weight loss, and heart defects, whereas FTO-overexpressing mice present obesity, weigh gain, and enhanced food intake." (PMID 34084770, 2021). "Interestingly, given the regulatory role of FTO in muscle differentiation and lipid accumulation in skeletal muscle, FTO may be considered a key regulatory factor specifically in sarcopenic obesity (high-risk disease characterized by both sarcopenia and obesity)." (PMID 35024366, 2021). "We constructed a genetic risk score (GRS) based on five genetic variants (MC4R rs17782313, BDNF rs6265, FTO rs1421085, TMEM18 rs7561317, and NEGR1 rs2815752) and examined its association with obesity-related traits in a sample of Pakistanis." (PMID 33859285, 2021). "With respect to genetic association of the four selected gene polymorphisms, FTO rs9939609 and MC4R rs17782313 were found to be associated with obesity." (PMID 34414818, 2021). "In this study, we performed a genetic association study employing various genetic models to assess the impact of FTO rs1421085 on obesity and dietary preference in individuals residing in Jakarta, Indonesia." (PMID 34743743, 2021). "Several potential obesity candidate genes and variants have been documented, including LEP and LEPR, which have been mainly implicated in monogenic obesity, as well as FTO, APOE, PPARG, and PPARA which have been mainly implicated in polygenic/common obesity." (PMID 34131278, 2021). "At the level of genotyping, the rs9939609 FTO marker analysis, shown to be the most contributing to obesity, yields all genotyped individuals except Mother to carry the risk allele." (PMID 33763108, 2021). "A comparison of the obesity and control groups revealed higher mean expression of FTO gene in obesity (317.37 ± 1.32 vs. 200.85 ± 1.4, FC = 1.58, p(B-H) = 0.008)." (PMID 34063412, 2021). "The aim of this research was to study the polymorphisms of two obesity-associated genes ADIPOQ and FTO that are also related to the pathogenesis of BC." (PMID 34345232, 2021). "IRX3 and IRX5 have emerged as a strong link between the non-coding genetic variations of the FTO gene and obesity." (PMID 34795556, 2021). "Generally, the combined effect of FTO rs9939609 and MC4R rs17782313 was significantly associated with obesity in various populations." (PMID 34414818, 2021). "This study provides metabolic data that focuses on the genetics of FTO in subjects with comparable and considerable obesity." (PMID 33684170, 2021).
Obesity (continued). "We find that FTO levels are elevated in fat mice, and that genes which lost m6Am marking under obesity are overly downregulated, including the two fatty-acid-binding proteins FABP2, and FABP5." (PMID 34893620, 2021). "Their variants affect the obesity risk by modulating the binding affinity of obesity-related transcription factors, such as STAT3, CEBPB, TCF7L2, FTO, and GATA2, and changing the phosphorylation of proteins, such as BDNF with the rs6265 risk allele." (PMID 34836030, 2021). "In the present study, the mRNA level of the FTO gene was significantly higher in children with obesity than in the control group." (PMID 34063412, 2021). "One study found that the FTO gene was positively correlated with the percentage of energy derived from fat, and negatively correlated with the percentage of energy from carbohydrates, indicating that the association between the FTO gene and obesity may be regulated by energy intake." (PMID 33668547, 2021). "Simultaneously, LTSB increased the effects of FTO rs9939609 and FTO rs8050136 on obesity and central obesity." (PMID 33668547, 2021). "Many diseases, including obesity, T2DM, and cancer, have been reported to be associated with the FTO gene." (PMID 34258276, 2021). "m6A and m6Am are two prevalent mRNA modifications which are target for removal by the fat mass and obesity gene FTO." (PMID 34893620, 2021). "Further validation and functional studies are needed to confirm our findings and to determine the underlying mechanisms by which FTO and TUB SNPs modulate susceptibility to obesity across racial and ethnic groups." (PMID 33983957, 2021). "The FTO mediates one common pathway of obesity and cancer via 6-methyl adenosine (m6A)-dependent demethylase activity." (PMID 34650918, 2021). "The current work significantly promotes our understanding of the mRNA modification metabolic effects by analyzing both of the mRNA modification targets of FTO (m6A and m6Am) in two different in vivo obesity mouse models." (PMID 34893620, 2021). "These genes were strongly connected, and FTO and MC4R acted as hub genes that affect the risk of obesity." (PMID 34836030, 2021). "This study clarified that leptin can regulate Plin5 M6A methylation by promoting FTO to affect the lipid metabolism and energy consumption, providing a theoretical basis for treating diseases related to obesity." (PMID 34638947, 2021). "For example, single-nucleotide polymorphisms (SNPs) in the FTO gene are associated with higher risk of obesity and type 2 diabetes, while SNPs in the MC4R gene are associated with increased fat mass and obesity risk." (PMID 33588846, 2021). "RBL2 plays a role in preadipocyte proliferation and differentiation and it has been suggested that a variant in the FTO gene is strongly associated with obesity and influences RBL2 expression, which impacts obesity risk." (PMID 34399688, 2021). "Serial GWAS studies on obesity-related traits in people of European descent have confirmed the important role of the FTO locus, and many other FTO SNPs in the intron 1 region have been reported, such as rs9930506, rs1421085, rs8050136, rs1121980, and so forth." (PMID 33304380, 2020). "Although these results are also compatible with the proposed role of FTO in modulating obesity, they powerfully highlight the importance of long-range gene regulation as a mechanism mediating the effect of genetic variants associated with CVD." (PMID 32603637, 2020). "Unfortunately, the mechanism for the correlation between FTO SNPs and obesity or cancer has been elusive." (PMID 33304380, 2020). "Recent studies have examined the relationship of the FTO gene with other PCOS-associated-phenotypes, including obesity, glucose intolerance, and insulin resistance." (PMID 32050935, 2020). "Among these genes, FTO has been reported as the gene with the strongest significant correlation with obesity." (PMID 33114268, 2020).
Obesity (continued). "This study explained the correlation between FTO SNPs and obesity by using the effect of the autonomous transformation of fat cells on thermogenesis." (PMID 33304380, 2020). "In contrast, others suggested that the FTO gene is under the control of nearby associated genes, chief among them IRX3 to be the main regulator in obesity." (PMID 33511112, 2020). "FTO promotes white adipocyte differentiation in vitro and development of obesity in vivo, whereas deletion of FTO impairs white fat adipogenesis both in vitro and in vivo." (PMID 32245957, 2020). "To investigate the involvement of gender and environment in relationship to FTO SNPs and obesity parameters, we conducted separate analyses for male and female subjects, as well as for urban and rural populations." (PMID 31915589, 2020). "As for FTO, it can participate in the disease progression of obesity and cancer in m6A-dependent post-transcriptional regulation, or by targeting mTOR." (PMID 33304380, 2020). "Demethylase FTO has been well known for its role in obesity and related diseases and can act as a transcription cofactor." (PMID 33173729, 2020). "It is therefore timely to consider the protective effect of EBF among children with elevated risk of overweight/obesity, where this risk is assessed by an obesity-specific GRS, and thus to extend our previous results on the FTO genetic variant." (PMID 32525877, 2020). "This evidence suggests FTO as the common genetic basis of obesity and cancer and a potential target for obesity and some cancers." (PMID 33304380, 2020). "The m6A demethylase FTO has been widely studied due to its established relationship with obesity, and it has been found to promote adipogenesis through multiple signaling pathways." (PMID 32733807, 2020). "The strong genetic correlations between obesity and FTO were found about 12 years ago and the FTO protein has been crystallized." (PMID 32747736, 2020). "Many genes associated with obesity are also increasingly known, such as the obesity (OB) gene, fat mass and obesity-related (FTO) gene, melanocortin receptor (MC4R) gene, etc.." (PMID 32111069, 2020). "Among them, human ALKBH5 and FTO protein have been demonstrated to function as m6A demethylases, which are involved in obesity, diabetes, and hypoxia response." (PMID 32933187, 2020). "As a result, RIDGE is recommended if E attenuates the adverse effects of most SNPs in a gene, as shown in the application of FTO × exercise interaction on obesity measures." (PMID 32457790, 2020). "Another limitation is that we only assessed one SNP, yet we note that the rs9939609 SNP is the most commonly examined FTO SNP and is in high linkage disequilibrium with other SNPs related to obesity and metabolic disease." (PMID 33348678, 2020). "In 2007, the GWAS study identified FTO as an obesity sensitivity gene, and multiple SNPs in the intron 1 region were strongly associated with BMI, body fat rate, waist circumference, hip circumference, and energy intake." (PMID 33304380, 2020). "New pleiotropic loci are identified, including signals from the cattle FTO locus mirroring its bystander effects on human obesity." (PMID 32111961, 2020). "In an attempt to understand the mechanism of FTO obesity modulation, it was suggested that an individual’s behavior toward food consumption is primarily regulated by this SNP." (PMID 31947684, 2020). "A meta-analyses study demonstrated the correlation between FTO rs9939609 and rs1421085 with obesity in Hispanic, Caucasian, and Asian populations." (PMID 31915589, 2020). "For instance, FTO (rs17817449) is positively correlated with obesity and plasma insulin, insulin resistance, percentage body fat and fat mass in a north Indian population." (PMID 32110378, 2020). "FTO, which was originally found to be involved in obesity and fat metabolism, was the first discovered m6A demethylase." (PMID 33505967, 2020).
Obesity (continued). "FTO proteins are involved in the development of obesity by affecting the m6A level of hormones related to eating or molecules related to adipogenesis." (PMID 33304380, 2020). "There are multiple proposed mechanistic regulatory roles of FTO in the development and progression of obesity." (PMID 33511112, 2020). "The FTO variants associated with intrauterine growth retardation (IUGR) and, in consequence, low birth weight, confer a predisposition to obesity later in life." (PMID 32747736, 2020). "Seven SNPs were also associated with obesity in Central Mexican children (SEC16B rs543874, OLFM4 rs12429545, rs9568856, FTO rs9939609, MC4R rs6567160, GNPDA23 rs1330484, and LMX1B rs3829849)." (PMID 31936053, 2020). "This review details this role and the molecular mechanisms of FTO in obesity and cancer, as well as its potential clinical applications as a therapeutic target." (PMID 33304380, 2020). "As far as we know, this is one of the first studies to present interactions between FTO SNPs rs3751812, rs8044769, rs8050136, and rs9939609 and macronutrient intake, and the effect of these relationships on obesity and obesity-related complications." (PMID 33114268, 2020). "We also include eight SNPs found slightly above the significance threshold in the FTO gene that are reported in several studies as obesity-related." (PMID 31888951, 2020). "To date, several of the most studied SNPs, including FTO (fat mass and obesity-related) gene, MC4R (melanocortin receptor) gene, and others, have made researchers increasingly aware of the impact of SNP on the development of obesity." (PMID 32357537, 2020). "In summary, more FTO inhibitors are displaying positive therapeutic effects in animal disease models, and represent promising therapeutic targets for obesity and cancer." (PMID 33304380, 2020). "More importantly, some drugs have been shown to inhibit obesity, and some cancers such as leukemia, glioblastoma, and breast cancer by targeting FTO." (PMID 33304380, 2020). "Selectively suppressing FoxO1 activity through the inhibition of FTO by entacapone provides the possibility to treat type II diabetes and obesity." (PMID 31936903, 2020). "In some of our previous studies, we also reported gender-specific association of the other variants such as MC4R rs17782313, FTO rs9939609, and LEP rs7799039 with overweight/obesity and related anthropometric traits in Pakistani females." (PMID 32419576, 2020). "The catechin EGCG, another natural compound rich in green tea, was found to play anti-obesity and anti-adipogenesis roles through the FTO-m6A-YTHDF2 axis." (PMID 33304380, 2020). "However, thus far the occurrence of genetic variants and expression of FTO in correlation with obesity, diabetes, and cancer in different populations has been widely discussed, but the understanding and characterization of the product of these genes—FTO protein is still poorly understood." (PMID 32747736, 2020). "Body composition indices such as BMI, fat mass and other obesity-related phenotypes are strongly regulated by the FTO gene." (PMID 33291384, 2020). "The study showed that the FTO gene locus, which has been well acknowledged as the major contributor to polygenic obesity in European populations, also provided the most prominent association signal in East Asian cohorts." (PMID 33193685, 2020). "FTO (rs9939609 T/A) is related to increased FTO expression, reduced m6A ghrelin mRNA methylation, and finally results in increased energy intake and obesity by upregulating the ghrelin expression." (PMID 32110378, 2020). "In summary, FTO can directly or indirectly target mTOR, thus regulating the occurrence and progress of obesity and cancer in a broad manner." (PMID 33304380, 2020). "However, the association between the FTO gene and dietary factors is still unclear and there is a scientific need to investigate the associations between environmental and genetic risk factors and their interactions and roles in obesity development and treatment." (PMID 33114268, 2020).
Obesity (continued). "Another typical obesity polymorphism is the FTO gene responsible for fat mass and an obesity-associated protein also known as alpha-ketoglutarate-dependent dioxygenase." (PMID 32272684, 2020). "The rs1421085 FTO is related to poor eating behaviors, and rs3751723 IRX3 is associated with obesity." (PMID 32651404, 2020). "Homogenates of the tissues crucial for the development of obesity and Type 2 diabetes (T2D) contained very low levels of the FTO protein." (PMID 32747736, 2020). "Genetic variants of the FTO and IRX3 genes are in high linkage disequilibrium and associated with obesity." (PMID 32651404, 2020). "For example, over-eating and physical inactivity have increased obesity in recent decades with different mechanisms e.g. increase the level of FTO gene expression." (PMID 31126299, 2019). "Although FTO is expressed in various tissues, its level is particularly high in the hypothalamus and this suggests that the hypothalamic FTO plays an important role in glucose metabolism as well as in obesity." (PMID 31728912, 2019). "There is strong support linking obesity, prostate and breast cancer, type 2 diabetes, and neurodegenerative diseases with increased expression of the FTO (obesity) gene." (PMID 31772698, 2019). "The role played by FTO and other obesity-related genes in the etiology of obesity has been reported." (PMID 31075924, 2019). "More research is needed to precise the contribution of SNPs in FTO and other obesity genes to impulsive behaviors in diverse ethnicities." (PMID 31772290, 2019). "Researches on the phenotypes of FTO knockout mice were mainly focused on the fat mass accumulation, body composition, energy expenditure and other obesity relative phenotypes in these studies." (PMID 31333841, 2019). "The ability of FTO to regulate RNA stability through modification with m6A was found to be related to obesity, with m6A modification being more common during adipogenesis." (PMID 31695458, 2019). "Although many genetic variants have been repeatedly associated with obesity, such as those located within FTO or MC4R genes, their ability to stratify obesity remains insufficient, as compared to traditional risk factors or familial resemblance." (PMID 31649740, 2019). "The relationship between FTO variants and impaired glucose tolerance, insulin resistance, and hyperandrogenism, that are prominent features of PCOS, are mediated via obesity and BMI." (PMID 32133054, 2019). "Top findings within the block involved well-known obesity genes such as the FTO, the CYP19A1 and the USF-1." (PMID 31527397, 2019). "Therefore, the LGI-Ob score as initially defined (i.e., including the influence of FTO polymorphism) would support a higher degree of confidence in the discriminant accuracy of LGI-Ob score identifying subjects having metabolic disturbances related with obesity." (PMID 30704070, 2019). "CRISPR/Cas9 also can be used to convert the obesity-promoting FTO gene in adipocyte precursor cells." (PMID 31762718, 2019). "A range of studies underlined its involvement in thermogenesis and cell metabolism and it was reported that FTO affects the obesity trait in age- dependent manner." (PMID 30871540, 2019). "This GWAS, with 1110 MO patients and 10,852 matched controls in Han-Chinese population, established that the top 6 SNPs (rs8050136, rs9939609, rs1421085, rs9941349, rs1121980, and rs9937354) were all located in the most replicable obesity gene: the FTO." (PMID 31852448, 2019). "So, FTO can be a main genetic factor in predisposing to PCOS, primarily via an effective role in obesity and BMI, and secondarily with influencing the metabolic parameters and hyperandrogenemia." (PMID 32133054, 2019). "The CXCL12 rs501120 C, FTO rs9939609 A, and LEP rs7799039 A alleles were significantly associated with T2D in the obesity group under a recessive inheritance model." (PMID 30764545, 2019).